ALKBH5 (alkB homolog 5, RNA demethylase)
Diseases named in the same sentence as ALKBH5 in open-access papers (continued):
Sharing a sentence is not in itself a finding about the gene and the disease.
tumor (continued). "We also found that the expression of ALKBH5 was correlated with the tumor stage and histological grades." (PMID 30987661, 2019). "FOXM1-AS knockdown impaired the GSCs growth similar to ALKBH5 knockdown, and rescue of tumor growth of GSCs by FOXM1 overexpression after depletion of ALKBH5 or FOXM1-AS further proved the critical role of FOXM1 in GSC tumorigenesis." (PMID 29374143, 2018). "m6A modification in mRNA of glioblastoma stem cells regulates their capacity of self-renewal and tumorigenesis, with overexpression of writers (METTL3 and METTL14) and downregulation of erasers (FTO and ALKBH5) inhibiting tumor growth." (PMID 30428628, 2018). "In our studies, loss of ALKBH5 expression significantly reduced the tumorigenicity of MDA-MB-231 cells and, in tumor-bearing mice, metastatic burden in the lungs was also significantly decreased." (PMID 27590511, 2016). "Targeting m6A writers (e.g., METTL3, METTL14), erasers (e.g., FTO, ALKBH5), or circRNA–miRNA interactions could restore regulatory balance and mitigate tumor aggressiveness." (PMID 41516402, 2026). "On the one hand, ALKBH5 modulates m6A modification of immune-related transcripts in tumor cells—including cytokines/chemokines, antigen presentation molecules, and immune checkpoint regulators-thereby indirectly shaping immune cell recruitment, activation, and effector function." (PMID 41562066, 2025). "Furthermore, hypoxia-inducible factors HIF-1α and HIF-2α strongly activate ALKBH5 transcription in hypoxic tumor microenvironments, highlighting the importance of microenvironmental cues." (PMID 41562066, 2025). "Additionally, ALKBH5 can act as a tumor suppressor to impede NSCLC progression by downregulating YTHDF1/2/3-mediated YAP expression and inhibiting miR-107/LATS2-mediated YAP activity." (PMID 40958857, 2025). "Understanding the multifaceted functions of ALKBH5 in tumor immunity provides new insights into precision immunotherapy and may guide the development of novel combination strategies to overcome resistance." (PMID 41562066, 2025). "Interestingly, ALKBH5 exhibits a tumor-suppressive role as a biomarker and correlates with immunotherapy responsiveness in hepatocellular carcinoma." (PMID 40986143, 2025). "Thus, ALKBH5 exerts both tumor-intrinsic and immune-intrinsic effects, together orchestrating tumor immune evasion and responsiveness to immunotherapy." (PMID 41562066, 2025). "ALKBH5 knockdown also similarly synergized with 5-FU to suppress tumor growth." (PMID 41390849, 2025). "Furthermore, the upregulated HIF1α promotes ALKBH5 overexpression, which can increase tumor-related lymphogenesis and lymph node (LN) metastasis of EOC in vivo and in vivo." (PMID 40958857, 2025). "Therefore, a deep understanding of the complex molecular structure and functions of ALKBH5 is essential for the strategic development of targeted activators or inhibitors for tumor therapy." (PMID 40958857, 2025). "In addition, ALKBH5 is a factor which regulates the expression of tumor stemness genes(e.g., SOX2) and impacts the pathogenicity of EC." (PMID 39904996, 2025). "In GC samples, ALKBH5 can function as a tumor suppressor gene." (PMID 40958857, 2025). "In addition, ALKBH5 regulates the tumor immune microenvironment (TIME) and participates in cancer progression." (PMID 40585991, 2025). "Therefore, inhibiting methyltransferase activity like METTL3 or activating demethylases like FTO or ALKBH5 can reduce m6A modification levels, thereby inhibiting tumor progression and resistance." (PMID 40740874, 2025). "Deletion of the M6A demethylase Alkbh5 has been shown to improve the tumor microenvironment." (PMID 40260303, 2025). "For instance, while ALKBH5 acts as a tumor suppressor in HCC, it may play an oncogene role in GC, which requires further investigation." (PMID 40958857, 2025). "Additionally, combination therapy also significantly downregulated RNA demethylase Alkbh5 in tumor-bearing mice." (PMID 41413253, 2025).
tumor (continued). "The function of ALKBH5 in cancer is complicated and debatable; reports suggest that it may have either tumor-suppressive or carcinogenic properties." (PMID 39781264, 2025). "Additionally, ALKBH5 overexpression in HCC enhances tumor progression by upregulating MAP3K8 through m6A modification, leading to JNK and ERK pathway activation." (PMID 40034695, 2025). "Accumulating evidence has demonstrated that ALKBH5 plays a critical role in tumorigenesis and tumor development, impacting tumor initiation, progression, and metastasis by regulating the mRNA metabolism of oncogenic and tumor suppressor transcripts." (PMID 40001461, 2025). "Moreover, the temporal dynamics of ALKBH5 during tumor progression and treatment are poorly defined, leaving open questions about when and how its modulation affects anti-tumor immunity." (PMID 41562066, 2025). "Furthermore, the dual roles of RNA modification effectors like FTO and ALKBH5 (which can act as both oncogenes and tumor suppressors) must be considered." (PMID 41373022, 2025). "Studies have demonstrated that ALKBH5 plays a critical role in a variety of immune system disorders by regulating multiple biological processes, including the development and defense functions of immune cells, and the tumor immune microenvironment." (PMID 40001461, 2025). "Consequently, tumors with low-ALKBH5 expression probably have reduced immune activation, suppressing anti-tumor immune responses." (PMID 40565233, 2025). "ALKBH5 functions as a tumor suppressor, which is consistent with previously published studies." (PMID 40341728, 2025). "YTHDF2 and ALKBH5 promote tumor progression through metabolic disorders and oncogene activation." (PMID 41446042, 2025). "Furthermore, within tumor cell subsets, co-expression of ALKBH5 with LGR5 (R = 0.39, P < 0.0001; n = 1295 cells) and CD133 (R = 0.25, P < 0.0001; n = 2867 cells) were observed." (PMID 41390849, 2025). "By analyzing the role of the modification of mRNA and ncRNA in cancer progression, researchers confirmed strong participation, mostly regarding METTL3/METTL14 complex, FTO, and ALKBH5, in tumor cell proliferation, invasion, migration, angiogenesis, metastasis, and drug resistance development." (PMID 41157107, 2025). "Knockdown of ALKBH5 enhanced effect of Oxaliplatin on suppressing tumor growth in POP66 and CSC28." (PMID 41390849, 2025). "Although both enzymes modulate the immune response through m6A-dependent mechanisms, accumulating evidence suggests that ALKBH5 exerts a more prominent role in shaping the tumor immune microenvironment, particularly by regulating immune checkpoint expression and T cell infiltration." (PMID 41562066, 2025). "Despite rapid progress, studies on ALKBH5 in tumor immunity remain limited." (PMID 41562066, 2025). "Specifically, we will first overview the biological functions and upstream regulation of ALKBH5, then discuss evidence and mechanisms according to immune cell type and tumor–immune interactions, and finally explore its prospects as a therapeutic co-target and biomarker in immuno-oncology." (PMID 41562066, 2025). "ALKBH5 knockdown in a 4T1 mouse tumor model improved immunotherapy efficacy and mouse survival." (PMID 39802639, 2025). "Interestingly, it has been reported that ALKBH5 can play a crucial tumor suppressive role in CRC as well." (PMID 40958857, 2025). "For example, these hybrid nanoparticles‐based ALKBH5 mRNA, which correlates with N6‐methyladenosine modification and affects tumor progression, largely inhibited tumorigenesis and prolonged the survival of preclinical tumor models by restricting glycolysis." (PMID 41476648, 2025). "Moreover, ALKBH5 influences the expression of a range of immune-related genes, thereby fostering a suppressive microenvironment that promotes tumor survival and metastasis." (PMID 39911396, 2025).
tumor (continued). "Accumulating evidence has revealed that ALKBH5 regulates immune cell recruitment and function, including CD8+ T cells, Tregs, NK cells, and tumor-associated macrophages, by modulating chemokines, cytokines, and metabolic pathways in an m6A-dependent or independent manner." (PMID 41562066, 2025). "Notably, ALKBH5 knockdown significantly reduces lactate accumulation and enhances tumor responsiveness to PD-1 blockade therapy." (PMID 40859309, 2025). "Flow cytometry analysis revealed that, compared to the Control group, the proportion of CD8+ T cells in tumor tissues was significantly increased in the ALKBH5-siRNA-BNVs and NGR-ALKBH5-siRNA-BNVs groups, while the proportions of Tregs and MDSCs were significantly reduced." (PMID 40585991, 2025). "Moreover, using tumor tissues from transgenic mice, we validated binding of ALKBH5 protein to FAM84A mRNA and its consequent effect on FAM84A expression." (PMID 41390849, 2025). "Current evidence suggests that ALKBH5 may play dual roles in tumor immune regulation, either enhancing antitumor immune responses or promoting tumor immune escape by shaping an immunosuppressive microenvironment." (PMID 41562066, 2025). "Targeting Alkbh5/Hspb1/ferroptosis axis may enhance anti-tumor effects in combination therapy, highlighting a potential therapeutic approach for HCC." (PMID 41413253, 2025). "Therefore, the overall impact of ALKBH5 on tumor immunity likely reflects a dynamic interplay between tumor and immune compartments." (PMID 41562066, 2025). "This suggests that ALKBH5 may be a potential target for regulating the tumor microenvironment and enhancing the effectiveness of immunotherapy." (PMID 39654883, 2024). "Interestingly, ALKBH5 can regulate the tumour microenvironment in response to tumour immunotherapy by inhibiting immune cell aggregation." (PMID 38572667, 2024). "In addition, there is a positive correlation between HBx and ALKBH5 in HBV-HCC tissues, and ALKBH5 knockdown significantly inhibits HBV-driven tumor cell growth and migration in vitro and in vivo." (PMID 38166832, 2024). "However, ALKBH5 plays a pivotal role in fostering the infiltration of CD8+ T cells within the tumor microenvironment through the NF-κB-CCL5 axis." (PMID 39199429, 2024). "To clarify whether ABCA1 participated in ALKBH5-dependent tumor progression and metastasis, we silenced ABCA1 in ALKBH5 stable knockdown SKCM A375 and A2058 cells." (PMID 38481816, 2024). "Meanwhile, the Kaplan-Meier curve showed that a low expression level of ABCA1 was accompanied by a better prognosis, suggesting that ABCA1 may be a tumor suppressor gene, which accorded with the logic that upstream ALKBH5 plays as a potential oncogene." (PMID 38481816, 2024). "In addition, with the assistance of IGF2BP1, ALKBH5 can also repress the post-transcriptional expression of Ly6/PLAUR domain-containing protein 1 (LYPD1) to suppress HCC tumor progression by mediating m6A demethylation." (PMID 38711100, 2024). "However, ALKBH5 knockdown significantly blocked the effect of FSH on the risk of distant metastasis and tumor number in xenograft mice." (PMID 38505602, 2024). "Although it is still unidentified whether PVT1 is critical in tumour growth, our results demonstrated that ALKBH5 might regulates tumour progression via PVT1 RNA." (PMID 38098223, 2024). "The versatile roles of ALKBH5 in various cancer types entail the modulation of numerous biological processes encompassing proliferation, metastasis, migration, invasion, metastasis, as well as tumor growth." (PMID 38501918, 2024). "Based on the results of our study and previous reports, we may reasonably speculate that the epigenetic modification of ABCA1 mediated by m6A demethylase ALKBH5 may affect tumor progression of SKCM via modulating cellular cholesterol homeostasis and autophagy." (PMID 38481816, 2024). "Jin proposed that the m6A regulator ALKBH5 may suppress tumor progression within the immune microenvironment via the RIG-1/IFNA axis." (PMID 38778403, 2024).
tumor (continued). "In addition, the RNA-binding proteins HuR and METTL14/ALKBH5 and their target genes form a feedback loop, regulating each other’s expression in cancer cells and participating in the regulation of tumor occurrence and metabolism." (PMID 39295872, 2024). "For example, overexpression of METTL3 may enhance the sensitivity of tumor cells to certain chemotherapy drugs, while high expression of ALKBH5 may lead to resistance." (PMID 39473440, 2024). "Thus, we first examined the expression levels of METTL3, METTL14, WTAP, RBM15, FTO, and ALKBH5 transcripts in tumor samples and corresponding normal samples using the GEPIA database." (PMID 38665783, 2024). "The tumor burden was higher in ALKBH5-overexpressing mice than in wild-type mice." (PMID 38872221, 2024). "Additionally, ALKBH5 with low expression was correlated with clinical tumor distal metastasis and lymph node metastasis in GC patients." (PMID 39009956, 2024). "Interestingly, the influence of ALKBH5 appears to be context-dependent, with its expression level acting either as an oncogenic promoter or a tumor suppressor, depending on the type of carcinoma." (PMID 38501918, 2024). "ALKBH5, another RNA demethylase, plays a role in many cancers by regulating a variety of biological processes, such as proliferation, migration, invasion, metastasis and tumor growth." (PMID 38166832, 2024). "Furthermore, targeting ALKBH5 was found to enhance the tumor immune microenvironment and boost the effectiveness of anti-PD-1 therapy by accelerating PD-L1 degradation." (PMID 38398118, 2024). "The m6A demethylase ALKBH5 is highly expressed in various types of tumor cells, including HNSCC." (PMID 38523155, 2024). "Notably, in cancer research, ALKBH5 inhibitors have demonstrated significant anti-tumor potential by promoting apoptosis and inhibiting the proliferation of tumor cells." (PMID 39192357, 2024). "Moreover, ALKBH5 has been reported to function as a tumor promoter in AML by post-transcriptionally modulating pivotal targets, such as TACC3, an oncogene related to prognosis in a broad spectrum of carcinomas." (PMID 38501918, 2024). "Knocking down ALKBH5 inhibited FOXM1 expression in GSCs, and restoring FOXM1 could counteract the consequences of inhibiting ALKBH5 on cell proliferation and tumor formation." (PMID 38398118, 2024). "Only ALKBH5 mRNA levels were significantly upregulated in tumor tissues." (PMID 38872221, 2024). "ALKBH5 has been reported to be upregulated in a variety of cancers including breast, lung, and epithelial ovarian cancers, where it plays an oncogenic role in tumor progression." (PMID 39281280, 2024). "However, relatively few studies have investigated the regulatory mechanisms of FTO and ALKBH5 in tumor development and angiogenesis." (PMID 39295872, 2024). "In addition, the RNA-binding proteins HuR, METTL14/ALKBH5, and their target genes form a feedback loop, regulating each other’s expression in cancer cells and participating in the regulation of tumor occurrence and metabolism." (PMID 39295872, 2024). "Knockdown of ALKBH5 increased the enrichment of m6A nearby the stop codon and 3’UTR region of CD274 mRNA, thereby promoting the decay of CD274 mRNA in a YTHDF2-dependent manner, but ALKBH5 has minimal inhibitory effects on tumor cell PD-L1 expression at the translational level." (PMID 38365891, 2024). "Moreover, elevated expression of ALKBH5 was correlated with larger tumor volume, higher TNM staging, and worse prognosis." (PMID 38503745, 2024). "In addition, ALKBH5 suppresses T cell proliferation and cytotoxicity by upregulating PD-L1 expression, effectively reducing tumor cell infiltration." (PMID 38711100, 2024). "The m6A eraser ALKBH5, when deleted, sensitises tumours to ICBs in vivo." (PMID 38545841, 2024).
tumor (continued). "For instance, ALKBH5, an m6A demethylase, impacts T cell function and tumor growth." (PMID 39512352, 2024). "In addition, relative to the sh-NC group, the levels of MIR205HG, JMJD2C, and ALKBH5 in tumor tissues were diminished in the sh-MIR205HG group (P < 0.01)." (PMID 38252669, 2024). "Additionally, accumulating studies have confirmed that the m6A demethylase ALKBH5 inhibits tumor growth, metastasis, invasion, and tumor angiogenesis in NSCLC by reducing YTHDFs-mediated YAP1 expression and inhibiting miR-107/LATS2-mediated YAP1 activity." (PMID 38053093, 2023). "Interestingly, ALKBH5 was the most significantly downregulated gene in tumor compared with normal tissues." (PMID 37612282, 2023). "Knockdown of ALKBH5 in vivo inhibited tumor growth primarily by destabilizing TIMP 3 mRNA." (PMID 38094306, 2023). "ALKBH5 regulates target gene splicing, leading to changes in lactate in the tumor microenvironment." (PMID 37781694, 2023). "We find that hypoxia-induced HIF-1α activates the ALKBH5 axis and accelerates tumor metastasis." (PMID 36632222, 2023). "The results revealed that ALKBH5 knockdown inhibited tumor growth and weight." (PMID 37858219, 2023). "Elsewhere, it was found that ALKBH5 could affect a mouse’s reproductive ability or tumour progression by regulating the m6A level of the downstream target genes." (PMID 36814204, 2023). "Next, we investigated the role of ALKBH5 overexpression and knockdown in tumor metastasis in vitro." (PMID 36632222, 2023). "Likewise, a recent study found that knockout of Alkbh5 inhibited tumor growth during anti–PD-1 treatment by regulating Mct4/Slc16a3 expression, lactate content, and suppressive immune cell accumulation in TME." (PMID 36960074, 2023). "Overall, our collective findings offer valuable insights into the critical role of the ALKBH5/FABP5/FASN/mTOR axis in tumor progression and uncover a potential mechanism linking lipid metabolism to development of CRC, providing novel therapeutic targets for future interventions." (PMID 37416772, 2023). "ALKBH5 may act as tumor suppressor in pancreatic cancer but on the contrary, as tumor promoter in osteosarcoma via upregulation of PVT1 lncRNA." (PMID 36969033, 2023). "They concluded that ALKBH5 had higher expression levels in both RCC tumour tissues and cell lines." (PMID 37284313, 2023). "Moreover, IHC staining of HPSCC samples from cohort 1 and cohort 2 indicated that the protein levels of TLR2 were reduced in tumor tissues when the expression of ALKBH5 was increased." (PMID 37612282, 2023). "Moreover, several studies have confirmed the close association of m6A regulatory factors ALKBH5, WTAP, and ELAVL1 with the pathological process of tumor invasion and metastasis." (PMID 37684273, 2023). "In addition, previous studies unveiled a more important function of ALKBH5 in the tumour immune microenvironment." (PMID 37203239, 2023). "In line with previous studies, these data suggest a tumour-promoting role of ALKBH5." (PMID 36859310, 2023). "Furthermore, ALKBH5-knockdown GSC cells in a mouse model demonstrated lower rates of tumour formation and an improved prognosis." (PMID 37444417, 2023). "We speculated that the mTOR signaling may promote the translation of ALKBH5 mRNA through certain protein kinases and increase the level of ALKBH5 protein, then affecting tumor metabolism." (PMID 37325047, 2023). "On the contrary, silencing ALKBH5 expression drastically inhibited tumour weight and growth." (PMID 37203239, 2023). "In addition, the number of tumor-forming lung lesions was also decreased in ALKBH5 knockdown groups." (PMID 38007439, 2023).